SUFU (SUFU negative regulator of hedgehog signaling)
Diseases named in the same sentence as SUFU in open-access papers (continued):
Sharing a sentence is not in itself a finding about the gene and the disease.
tumor (continued). "However, elevated SUFU permits the generation of more GLI activators, thereby rendering the SHH pathway to be activated to higher levels and exacerbating the consequence of the original tumor-driving mutations." (PMID 38358805, 2024). "Such an effect was likely caused by the inability of the SuFuK321/457R mutant to suppress the tumour cell proliferation as suggested by increased expression of Ki67 and Gli1 observed in mice engrafted with the SuFuK321/457R mutant compared to mice engrafted with wild-type SuFu." (PMID 29515120, 2018). "Of these, 25 have a mutation frequency above 5% in one or more tumour type while the other three, ERBB2, FGFR2 and SUFU, have biologically plausible mutations but a low mutation frequency (mutation frequencies in all available data are; 1.2% for ERBB2, 2% for FGFR2 and 1.6% for SUFU)." (PMID 16421597, 2006). "Suppressor of fused (SUFU), a core member of SHH signal transduction, functions as a tumour suppressor by inhibiting the activity of transcription factors glioma-associated oncogene homologue (GLI)-triggered SHH signalling pathway." (PMID 41797322, 2026). "For example, lncRNA GAS5 in TNBC patients is related to tumor resistance to PTX, which induces apoptosis by regulating the miR-378a-5p/SUFU signal pathway." (PMID 36387210, 2022). "Previously, we found that SUFU was negatively regulated by SPOP–PTEN axis and acted as a tumor suppressor in ccRCC." (PMID 34021128, 2021). "Deletion of a locus on 10q24.32 containing SUFU (Suppressor of Fused), ARL3 (ADP Ribosylation Factor Like GTPase 3) and TRIM8 (Tripartite Motif Containing 8) was observed in 25/118 tumours (21%)." (PMID 34580349, 2021). "However, there are cases where somatic SUFU or PTCH1 variants were identified in tumor DNA but could not be confirmed in the germline." (PMID 34888241, 2021). "Each loss of function variant, however, did not significantly suppress the growth of ASZ001 cells, confirming that SUFU requires the ability to bind and inhibit GLI in order to suppress tumor cell growth." (PMID 28030567, 2016). "As expected, SUFU WT suppressed the growth of the ASZ001 cells compared to control nucleofected cells after 20 hours, consistent with its role as a tumor suppressor." (PMID 28030567, 2016). "Our work continues to delineate the interaction between SUFU and GLI1, and specifies which residues are important in the pathogenesis of tumor growth." (PMID 28030567, 2016). "miR-378a-3p can block the tumor-suppressive Fus1 (TUSC2) and SUFU genes, leading to increased cell survival and tumor growth." (PMID 25760330, 2015). "In a recent work from the Children’s Oncology Group (COG) in highly-differentiated fusion negative tumours, four out of 22 patients harboured mutations in the Hh pathway (three in PTCH1, one in SUFU)." (PMID 36765685, 2023).
tumor (continued). "Mutations within the components of the HH pathway, for example, membrane receptor proteins PTCH1 and SMO, non-membrane receptor proteins, such as SUFU and REN (KCTD11), disrupt the feedback loop causing activation of HH pathway and tumor progression." (PMID 33637972, 2021). "In our previous study, we found that SUFU expression was downregulated in GC relative to adjacent normal tissues, and that this expression was negatively related to the tumor stage." (PMID 33848981, 2021). "To explore the potential clinical significance of SUFU downregulation by SPOP, we first performed the immunohistochemical staining to evaluate the levels of SPOP and SUFU among 16 different types of cancers, using human tumor tissue microarrays." (PMID 34021128, 2021). "Taken together, our results characterized a negative correlation between SPOP and SUFU in ccRCC, and suggested a potential tumor suppressor role for SUFU in this disease." (PMID 34021128, 2021). "Notwithstanding, the tumor-promoting role of SUFU revealed in our studies does not run contradictory to its status as a tumor suppressor, as the SHH pathway could be activated by way of derepression in MBs with SUFU mutations." (PMID 38358805, 2024). "Likewise, tumor-derived substitutions in a stretch of 12 amino acids running from V107 to G118 did not affect binding to SUFU." (PMID 35831023, 2022). "Consistently, tumor biopsies of BCC showed a 10q deletion containing SUFU, which was associated with the partial loss of SUFU function but was not sufficient to drive resistance to vismodegib in the absence of other co-occurring alterations, such as focal GLI2 amplifications." (PMID 30558232, 2018). "Independent of tumor characteristics, such as histology and grades, higher expressions of SHH, PTCH1, PTCH2, and GLI1 have shown beneficial prognostic influence, whereas GLI2, GLI3, and SUFU are correlated with adverse clinical outcomes in OC patients." (PMID 40565349, 2025).
cancer (59 papers, 2007 to 2026). A tumor composed of atypical neoplastic, often pleomorphic cells that invade other tissues. "Little is known about risks associated with germline SUFU pathogenic variants (PVs) known as a cancer predisposition syndrome." (PMID 35768194, 2022). "The results showed that ATM, CHD4, FAT1, KMT2D, MED12, NF2, and SUFU were the most frequently mutated cancer-related genes." (PMID 33193598, 2020). "Oncogenic activation of the Hh pathway—for example, as a result of mutations in SMO and SUFU—is required for the progression of some cancers." (PMID 32053600, 2020). "Loss of SUFU has been shown to promote tumorigenesis and progression in many cancers in mammals." (PMID 34021128, 2021). "SMO and SUFU mutations have been reported in a variety of cancers." (PMID 32053600, 2020). "Differences in GLI1 and SUFU gene expression levels among control tissue, borderline tumors, and carcinomas have been reported by other studies." (PMID 40565349, 2025). "On comparison, we found that 53 (82.81%) of the malignant tumor tissues that displayed reduced expression at the mRNA level also showed decreased SuFu expression at the protein level." (PMID 36831076, 2023). "Our data reveal that SuFu overexpression increases cancer stemness properties together with a migratory phenotype." (PMID 36091108, 2022). "Our data showed that the expression of SUFU protein was significantly elevated in the ROC1-knocked down 5637 cancer cells compared with that of the control cells." (PMID 33499884, 2021). "Compared to the matched adjacent normal tissues, SNEP1 expression was greater in cancer tissues, accompanied by relatively lower expression of SuFu." (PMID 33608498, 2021). "SUFU and GLI3 have been linked to Hedgehog signaling, another pathway in cancer, suggesting a putative explanation for the link between TGF-β and Hedgehog signaling." (PMID 27096930, 2016). "We first investigated the expression of SUFU in normal tissue and cancer cell lines by real-time RT-PCR." (PMID 22666390, 2012). "The most common mutations in these tumors include loss-of-function mutations in PTCH and SUFU, gain-of-function mutation in SMO, or gene amplifications in GLI1 and GLI2, as shown in mouse or human cancers, resulting in uncontrolled Hh activity and promoting tumorigenesis." (PMID 37213270, 2023). "We suggest that this MAPK-mediated SUFU release might be an important component of the molecular mechanism by which MAP kinases activate GLI1 in cancers and other pathological scenarios." (PMID 35831023, 2022). "In addition, GLI-1 is an important therapeutic target in cancer, including through its interaction with SUFU." (PMID 35501860, 2022). "AR, IGF1R, PDGFRB, PIK3R1, and SUFU involved in KEGG pathways in cancer." (PMID 34208639, 2021). "Furthermore, knockdown of SUFU expression partially rescued the ROC1 knockdown-suppressed SHH activity as well as cancer cell growth inhibition." (PMID 33499884, 2021). "A regulator of GLI activity is SUFU, which binds to all three GLIs and controls the expression of downstream proteins, thereby arresting cell proliferation and affecting other properties of cancer cells." (PMID 32867229, 2020). "However, the role of HHIP in cancer is poorly understood, although it is well known that inactivating mutations in PTCH1 or Suppressor of fused homolog (SUFU) or activating mutations in SMO contribute to tumorigenesis through HH signaling activation." (PMID 30241415, 2018). "For this, additional experiments need to be performed to evaluate the efficacy of IMQ in cancer cells expressing drug-resistant variants of SMO or lacking SUFU, the key negative regulator of GLI." (PMID 25594066, 2014).
cancer (continued). "In this article, our main objective was to find out the effects of those cross talking molecules, such as RAS, TWIST, ERK12, NOTCH1 or the loss of functions of few tumor suppressor proteins such as SUFU, GAS1, SUFU, NUMB, SNO in the three types of cancer scenarios discussed earlier." (PMID 23935937, 2013). "As SUFU negatively regulates the hedgehog pathway, targeting the abnormal activity of SUFU holds promise as a therapeutic strategy to impact GLI1, a pivotal contributor to the advancement of multiple cancer types via the hedgehog signaling pathway." (PMID 39059063, 2024). "Some cancer-relevant genes on chromosome 10 include PTEN and SUFU, negative regulators of PI3K and Hedgehog signaling respectively, with deletions reported in prior studies of MCC." (PMID 32188490, 2020). "Pathways related to nervous system development (FDR = 5.8 × 10−8) were enriched for the PID-N genes ASCL1, CTNNB1, ID2, SUFU, and TERT that have known roles in cancer, complementing the PID-C genes NOTCH1, PTEN, and RHOA that also have known cancer roles." (PMID 32024854, 2020). "Moreover, in human cancers, genetic alterations of HH-related genes such as PTCH1, SMO, and SUFU significantly influence cilia-dependent tumorigenesis." (PMID 37510333, 2023). "However, the role of the HH-GLI1 pathway in cancer and the activation mechanism of GLI1 in HH signalling after dissociation from its inhibitor, SUFU, are not fully understood." (PMID 30675521, 2019). "However, the role of the HH-GLI1 pathway in cancer and the activation mechanism of GLI1 in HH signalling after dissociation from SUFU are not fully understood." (PMID 30675521, 2019). "SUFU blocks the pathway by sequestering Gli transcription factors in the cytoplasm, and to our knowledge, its methylation has not been studied in cancer so far." (PMID 27553089, 2017). "Overall, this work adds to our understanding of the structure and function of SUFU and GLI, expands our knowledge of BCC mutations, and reinforces the idea that highly mutated cancers contain many passenger mutations of no known functional relevance." (PMID 28030567, 2016). "Aberrant activation of HH signaling in human cancers could result from genetic alterations in pathway components, including PTCH1, SMO, SUFU and GLI1." (PMID 23826113, 2013). "Up-regulation of NF1, RB1 and SUFU shows a negative effect on cancer growth, consistent with our previous report." (PMID 21765906, 2011). "As a mechanism of crosstalk, potentially relevant to cancer and developmental signaling, ERK2 MAP kinase phosphorylates the Hedgehog-pathway transcription factor GLI1 on three sites, promoting release of the negative regulator SUFU and the consequent activation of GLI1." (PMID 35831023, 2022).
GI tumor (1 paper, 2016). "SUFU is a negative regulator of Hedgehog signaling pathways, which have been implicated in directing mesenchymal growth within the GI tract and, when overexpressed, in GI tumor carcinogenesis." (PMID 27974047, 2016).
SUFU also shares sentences with these, for which no sentence is quoted: autosomal dominant disease (2 papers); chondrosarcoma (2); Ciliopathies (2); colorectal tumor (2); Alzheimer disease (1); astrocytoma (1); bacteremia (1); brain cancer (1); cardiovascular diseases (1); Cerebellar medulloblastoma (1); chronic GVHD (1); clear cell renal cell carcinoma (1); CMMR-D syndrome (1); colorectal cancer (1); Cowden syndrome (1); developmental delay (1); diabetes (1); Ellis-van Creveld syndrome (1); endometrial cancer (1); esophageal adenocarcinoma (1); Ewing sarcoma (1); fibroma (1); fibrous tumour (1); genetic disorder (1); Hepatic fibrosis (1); hepatocellular carcinoma (1); kidney cancer (1); Li-Fraumeni syndrome (1); neurocutaneous disorder (1); neurodevelopmental disorder (1).
A further 17 diseases each share a sentence with SUFU in 1 paper.